INS (insulin)
Diseases named in the same sentence as INS in open-access papers (continued):
Sharing a sentence is not in itself a finding about the gene and the disease.
Insulin resistance (continued). "Whole body insulin resistance may therefore equate to a different, but overlapping set of metabolic derangements and may reflect tissue-specific differences in insulin signaling." (PMID 24555815, 2014). "We used median regression to assess the associations between urinary phthalate metabolites and fasting blood glucose (FBG), fasting insulin and Homeostatic Model Assessment of insulin resistance (HOMA-IR), controlling for urinary creatinine as well as several sociodemographic and behavioral factors." (PMID 24499162, 2014). "Insulin resistance may be one of the suppositional reasons, and the increased insulin secretion may be considered as a compensatory response to overcome the insulin resistance." (PMID 24971368, 2014). "Both males and females developed metabolic syndrome as a consequence of the CAF feeding, showing overweight, higher adiposity and liver weight, increased plasma levels of glucose, insulin and triglycerides, as well as insulin resistance, in comparison with their respective controls." (PMID 24482678, 2014). "Indeed, mice selectively lacking RANK in the hepatocyte (RankLKO) were protected by high-fat diet induced insulin resistance and showed fasting glucose and insulin concentrations similar to those of RankWT mice fed a normal-fat diet." (PMID 25140176, 2014). "Besides, fasting insulin levels of the left C57BL/6 J mice in each group also showed that atorvastatin was beneficial for amelioration of insulin resistance (P < 0.05 vs. con)." (PMID 24950764, 2014). "Although deregulation of these phosphatases may lead to insulin resistance, their functions are a part of reversible switches critical for normal insulin action." (PMID 24997070, 2014). "In addition, changes in waist circumference (p=0.004), hip circumference (p=0.000), FBS (p=0.06), plasma insulin (p=0.007) and insulin resistance (p=0.007) had significant interaction with the time between the groups." (PMID 25560330, 2014). "For example, HFD promoted lower levels of 1,5-anhydroglucitol (1,5-AG), a marker of glycemic control, which is indicative of systemic insulin resistance and is in accordance with our previous studies showing systemic glucose intolerance and insulin insensitivity in this model." (PMID 25505420, 2014). "On the other hand, several observations clearly show that insulin resistance alone is not sufficient to lead to type 2 diabetes in the absence of a beta-cell defect associated with abnormal insulin secretion." (PMID 25232350, 2014). "Future studies are required to determine whether the IRS2-dependent stimulatory insulin signaling in PTs is preserved in common forms of insulin resistance." (PMID 24982885, 2014). "Similarly, obese participants had greater triglycerides, insulin, and homeostatic model assessment-insulin resistance concentrations (P = 0.02–0.002)." (PMID 25177497, 2014). "Consequently, insulin resistance is a common pathological state in which target cells fail to respond to normal stimuli from circulating insulin." (PMID 24466104, 2014). "In addition, recombinant CT-1 treatment corrected insulin resistance and reduced adiposity in ob/ob and high-fat diet receiving mice, pointing to a key regulatory role of CT-1 in insulin sensitivity and lipid metabolism." (PMID 25025664, 2014). "Moreover, we revealed that 4-Hydroxymephenytoin, a core component of Ge-Gen, was involved in the antidiabetic ingredients of GGQLD, which can stimulate endogenous insulin secretion and ameliorate insulin resistance in 3T3-L1-based insulin resistance models." (PMID 24527048, 2014). "Moreover, as serum MK levels were significantly elevated in obese subjects and correlated with BMI, further analysis of its relationship with insulin sensitivity will provide additional evidence for its actions on insulin resistance in humans." (PMID 24516630, 2014).
Insulin resistance (continued). "C5L2 knock-out mice show increased food intake, increased WAT, altered glucose/insulin metabolism, and change in adiponectin and insulin gene expression, which could lead to the development of insulin resistance." (PMID 24393631, 2014). "Insulin-stimulated glucose uptake is severely impaired in T2D, which may be due to insulin resistance in skeletal muscle and adipocytes, a key feature of T2D." (PMID 25549240, 2014). "Abnormality in insulin recognition can lead to insulin resistance." (PMID 25421245, 2014). "As LRP2 has a role of renal reabsorption for its ligands such as insulin, LRP2 variants could have an association with SUA variation with increasing insulin resistance." (PMID 24366390, 2014). "Therefore, the deletion of HIF-1α in adipocytes improved glucose tolerance via two distinct pathways: decrease of insulin resistance and improvement of insulin secretion." (PMID 24705496, 2014). "The changes in IR structure and autophosphorylation detected in this study make it possible that the level and duration of insulin stimulation may act partially at the IR to initiate or progressively worsen insulin resistance." (PMID 25259572, 2014). "However, the failure of pancreatic islet insulin secretion to compensate for insulin resistance is the critical pathology that ultimately leads to T2D." (PMID 24505268, 2014). "Sitagliptin treatment was able to completely reduce tissue TRIB3 expression, which might be a key mechanism for the decline of insulin resistance and improvement of insulin secretion observed in the diabetic rats under sitagliptin treatment." (PMID 24650557, 2014). "We and others have previously reported that cadmium concentrations in blood or urine are associated with HbA1c, but not with plasma insulin, blood glucose, measures of insulin resistance and pancreatic insulin production." (PMID 25393737, 2014). "Several days later, the mice were subjected to an insulin tolerance test to explore whether the impaired glucose tolerance in MK2−/− mice could be ascribed to insulin resistance." (PMID 25233471, 2014). "Early-stage insulin-resistance and related mild glucose intolerance may be compensated by increased insulin secretion." (PMID 24991532, 2014). "In conclusion, our findings of increased ceramide biosynthesis with insulin provide a possible mechanism to partly explain the substantial evidence linking hyperinsulinemic conditions (e.g., insulin resistance and type 2 diabetes) to multiple disease states, especially vascular complications." (PMID 24949486, 2014). "Insulin resistance may mimic to some degree the loss of insulin in T1DM, and insulin resistance in Sertoli cells may hypothetically be associated with a decrease in spermatogenesis." (PMID 24885899, 2014). "Insulin resistance is defined as the decreased ability of tissues to respond to insulin action." (PMID 24733068, 2014). "Insulin resistance is characterized by a decrease in insulin signaling and action." (PMID 25295245, 2014). "Consistent with the critical role for liver fat in the pathogenesis of hepatic insulin resistance and type 2 diabetes, recent studies showed that caloric restriction rapidly lowers hepatic fat content and improves hepatic insulin sensitivity in type 2 diabetes patients." (PMID 24632889, 2014). "Since AGEs were shown to induce insulin resistance in several cell types and insulin sensitivity has been correlated with GLP-1 secretion, we investigated whether glycated serum of high glucose might be associated with insulin resistance in GLUTag cells." (PMID 24648662, 2014). "BMI, blood pressure, insulin resistance (fasting insulin, HOMA-IR) and lipids were assessed." (PMID 25117750, 2014). "None of the investigated traits, i.e. 2 h glucose (OGTT), Hb1Ac, fasting glucose, fasting insulin, insulin resistance (HOMA-IR), β-cell activity (HOMA-B), total/HDL/LDL cholesterol, triglycerides and type 2 diabetes, demonstrated evidence for association (all P > 0.05) with rs2149954." (PMID 24688116, 2014).
Insulin resistance (continued). "In summary, our findings that apoAI can improve insulin sensitivity through anti-inflammatory effects in hepatocytes may lead to novel approaches for the treatment of insulin resistance." (PMID 24347528, 2014). "While the absence of DUSP2 had no impact on obesity-associated inflammation and insulin resistance in male mice, we did observe a small, but significant improvement in the insulin sensitivity of female DUSP2-deficient mice fed the HFD." (PMID 25375135, 2014). "In addition, it was observed that a hyperinsulinemia, hypercholesterolemia, higher HOMA-IR and lower insulin sensitivity exhibited in offspring rats of LPS group, High-fat group and LPS+High-fat group, which suggest higher insulin resistance in these groups." (PMID 24498431, 2014). "Regarding in vivo investigation of (compound-induced) metabolic dysregulation, such as insulin resistance, a number of methods have been developed to measure glucose and insulin kinetics, of which the hyperinsulinemic euglycemic clamp (HIEC) is considered as the ‘gold standard’." (PMID 25181348, 2014). "However, they had comparable levels of fasting plasma glucose, fasting plasma insulin, blood lipid, and insulin resistance (HOMA2-IR) by comparison to those with other types of primary ZHENG." (PMID 24711854, 2014). "Consequently, glucose levels are lower in pregnant women because of hyperplasia of the insulin-secreting pancreatic beta cells, increased insulin secretion, and an early increase in insulin sensitivity followed by progressive insulin resistance." (PMID 24962444, 2014). "Although deterioration of insulin secretion and aggravation of insulin resistance are two major defects in the pathogenesis of diabetes, the clinical features of type 2 diabetes cases in Asia are explicitly different from those of type 2 diabetes cases in other parts of the world." (PMID 25138993, 2014). "Notably, however, the vasodilator action of insulin is reported to be attenuated in insulin resistance." (PMID 24982885, 2014). "PKCα was abundantly expressed in our cells, suggesting that we may have identified a candidate, which would be partially responsible for the development of glucose/insulin mediated insulin resistance." (PMID 25330241, 2014). "Although insulin resistance may be partially compensated by increasing the levels of insulin in the blood, insulin secretion remains insufficient to overcome the lesions caused by obesity and high levels of blood sugar." (PMID 25371752, 2014). "Both cases support the concept that decreased intramyocellular acylcarnitine can ameliorate insulin resistance, which is consistent with the significantly increased acylcarnitine level in the muscle of insulin resistant Cpt1b+/−mice after prolonged HFD feeding." (PMID 25580367, 2014). "Excess gestational weight gain increases the normal insulin resistance that occurs in pregnancy and may also affect other hormones that regulate nutrient transport across the placenta resulting in increased fetal insulin secretion, growth and adiposity." (PMID 25084967, 2014). "Given that insulin acts to increase lipogenesis, it might be thought that, in conditions of insulin resistance, fatty acid synthesis would be decreased." (PMID 25371775, 2014). "On the other hand, it is interesting that GHD treated adolescents have the well-known higher insulin resistance at fasting but it is coupled with a compensatory insulin secretion both at fasting, measured as HOMA-β, and during OGTT, measured as INS with also a stable DI." (PMID 24498035, 2014). "In addition, we found that MCK-MCP1 transgenic mice had elevated glycemia and ip insulin tolerance test revealed that these mice showed systemic insulin resistance." (PMID 25337938, 2014). "Besides hyperlipidemia, this hamster model also developed mild insulin resistance, particularly in the liver, manifested by elevated basal insulin excursion and lowered ISI." (PMID 24759758, 2014).
Insulin resistance (continued). "Impaired stimulation of carbohydrate oxidation and impaired inhibition of lipid oxidation in response to insulin could precede peripheral insulin resistance." (PMID 23934358, 2014). "Our observation of an additive increase in ceramides with insulin and palmitate together in muscle cells is noteworthy because it reflects an environment that typifies insulin resistance—elevated insulin, increased circulating fatty acids, and increased muscle ceramides." (PMID 24949486, 2014). "The decreased responsiveness to insulin in adipocytes may promote fatty acid release into the circulation, leading to hepatic and muscle insulin resistance." (PMID 24918199, 2014). "The interaction of free T4 with insulin resistance on bilirubin may have pathophysiological relevance since lower thyroid functional status, impaired insulin sensitivity, and low bilirubin are all characterized by enhanced oxidative stress." (PMID 24595410, 2014). "Indeed, in our studies of insulin resistance initiated by chronic insulin exposure, Y972 and Y1162, 1163 were refractory for re-stimulation by insulin." (PMID 25259572, 2014). "Evidence of the close relationship between copper and insulin resistance is also provided by a study in which treatment with a copper-chelating agent, tetrathiomolybdate, decreased serum copper ion, glucose, insulin concentrations, and also triglyceride levels." (PMID 23708056, 2014). "AS160 regulates insulin-stimulated glucose uptake in skeletal muscle, primarily by stimulating the translocation of GLUT4 to the cell surface and decreased AS160 signaling has been associated to insulin resistance." (PMID 25000528, 2014). "In order to examine whether BLyS is of functional relevance in terms of development of insulin resistance in humans in vivo, the effect of BLyS on human insulin sensitivity was examined in a translational research approach." (PMID 24728308, 2014). "In addition, these products induced insulin resistance as measured by a decrease in insulin-mediated activation of key insulin-signaling proteins, such as Akt and insulin receptor substrate-1." (PMID 24432004, 2014). "Adipose inflammatory changes included increased proinflammatory to antiinflammatory macrophage ratio and insulin signaling abnormalities, which could lead to insulin resistance." (PMID 24508979, 2014). "Because of the insulin-sensitizing effects, low levels of adiponectin might further aggravate insulin resistance in GDM." (PMID 25202741, 2014). "Since exercise reduces insulin resistance and facilitates glucose metabolism, several studies have attempted to establish a relationship between exercise, adiponectin levels (or the expression of adiponectin receptors), and improvements in insulin function." (PMID 24563869, 2014). "Impairment of GLUT4 expressions and GLUT4 translocation and/or insulin signaling may affect insulin-stimulated glucose uptake, and that would result in insulin resistance and hyperglycemia." (PMID 25140189, 2014). "Determination of whether TLR4 signaling can be activated in the heart by insulin may shed light on the pathogenesis of diabetic cardiomyopathy, a process that is often complicated by obesity and insulin resistance." (PMID 25101057, 2014). "Insulin resistance and secondary hyperinsulinemia could however also directly lead to higher red blood cells, since insulin and erythropoietin have synergistic effects in stimulating erythroid colony proliferation." (PMID 25000394, 2014). "Since insulin resistance involves impairment of normal glucose and insulin homeostasis, metabolomics analyses following an OGTT are an attractive means to identify biochemical pathways associated with individual variability in insulin action and blood sugar control." (PMID 24416208, 2014).
Insulin resistance (continued). "Glucocorticoids (GCs) are highly effective anti-inflammatory agents but have been precluded in type 1 diabetes and in islet transplantation protocols because they exacerbated insulin resistance and suppressed β-cell insulin secretion at the high-doses employed clinically." (PMID 25352830, 2014). "Although the biological effects of PFOS on the elevated levels of fasting serum glucose and insulin levels were observed in both pups and adults of F1, the phenotypes of insulin resistance and glucose intolerance were evident (i.e. HOMA-IR index and glucose AUC) in the F1 adults." (PMID 24498028, 2014). "Vitamin D insufficiency induced alterations in the calcium flux of pancreatic b-cells thus reduced insulin secretion and this might influence on insulin resistance (IR)." (PMID 25350669, 2014). "The BCAA-related signature also displayed a significant linear relationship to insulin resistance, correlated with HbA1c levels in weight-matched type 2 diabetic vs. non-diabetic women, and predicted improvements in insulin sensitivity during weight loss." (PMID 25050624, 2014). "If the attenuation in insulin resistance is in fact primarily due to local muscle change in response to high-intensity resistance training, then perhaps the larger the number and size of muscles stimulated the greater the improvement in insulin action." (PMID 24707476, 2014). "It has been proposed that insulin dose could discriminate patients with insulin resistance; however, this is unreliable because it is inaccurately reported by patients and the potential effect of residual endogenous insulin secretion." (PMID 24594198, 2014). "Type 2 diabetes (T2D) is a metabolic disorder characterized by hyperglycemia caused by the relative lack of insulin production, due to the exhaustion of pancreatic beta cell function after the establishment of insulin resistance." (PMID 25214711, 2014). "This could be explained by the different postreceptor defects leading to insulin resistance and the different patterns of impaired insulin secretion between patients with DM-NAFLD and those with T2DM only." (PMID 24397589, 2014). "However, EA stimulation at the Zhongwan/Gwanyuan acupoint cannot reduce plasma glucose levels in type II diabetic rats with higher insulin resistance induced by repeated injection of insulin." (PMID 25024728, 2014). "Changes in calcium influx in primary insulin target tissues may contribute to peripheral insulin resistance." (PMID 24868538, 2014). "Disturbances of the insulin signaling pathway might affect brite adipocyte recruitment and/or activity, which could aggravate insulin resistance in a type 2 diabetic setting." (PMID 25313899, 2014). "In line with other reports showing that FF-leptin levels are predictive of fertilization rates, lower than normal FF-leptin levels in NOW-PCOS may explain their lower fertilization rate and this may be related to the level of insulin and/or insulin resistance." (PMID 24895638, 2014). "At baseline, insulin resistance, defined as an area under the curve of insulin greater than 12,000 μUI/ml × 180 min on the oral glucose tolerance test, was seen in 8 of the 19 subjects, 3 out of 10 of those who subsequently received Metformin and 5 out of 9 of those in the placebo group." (PMID 25304843, 2014). "Across classes of BMI, PCOS patients had greater insulin resistance than matched controls (p<0.0001 for all the comparisons), but they showed higher fasting and total insulin secretion than their age, BMI and insulin resistance-matched peers (p<0.0001 for all the comparisons)." (PMID 24705280, 2014). "Clinic evidence has indicated a significant positive association between 20-HETE excretion and BMI, and obesity has been linked with insulin resistance, which may be a rational explanation for the inhibitory effect of 20-HETE on insulin vascular action." (PMID 24763529, 2014).